FN1 (fibronectin 1)
Diseases named in the same sentence as FN1 in open-access papers (continued):
Sharing a sentence is not in itself a finding about the gene and the disease.
cancer (continued). "The expression of mesenchymal markers associated with cancer progression, such as FN1, VTN, and ITGA5, was markedly increased (between 20- and 50-fold)." (PMID 32699630, 2020). "The FN1 gene, a glycoprotein involved in cellular adhesion and migration processes, was denoted to have an association with the pathway in cancer." (PMID 31127138, 2019). "The −77VNTR has a regulatory role on the expression of a secondary, truncated, HCC-specific transcript, which in turn coincides with disruptions in cancer-associated pathways and in FN-1 expression modifications." (PMID 29713327, 2018). "FN1 is one of many ECM proteins with aberrant expression in cancer, where it is associated with angiogenesis, invasion via matrix metalloproteinase activation, self-renewal, proliferation, and resistance to therapy, and high expression correlates with poor survival." (PMID 35842572, 2022). "Meanwhile, FN1 has been linked to cancer patients’ prognosis and therapy responsiveness." (PMID 36081567, 2022). "In cancer, FN1 is expressed by cancer-associated fibroblasts and by the cancer cells." (PMID 36146635, 2022). "LIG1 (which was also found to be a component of the base excision repair pathway in KEGG analysis of MMNK-1 cholangiocytes) and FN1, which are implicated in diseases and cancer, were significantly correlated genes with the increase in 1,2-DCP level in the co-cultured MMNK-1 cells." (PMID 35780190, 2022). "Mutations at the FN1 gene have been associated with fibronectin glumerulopathy—a kidney disease that results in irreversible kidney failure, while there is an association with various types of cancers, including liver cancer but mostly thyroid cancer." (PMID 34442866, 2021). "The conclusions have been variable, probably because patients have not always been classified in terms of the precise origin of neoplastic tissues and FN1 level in cancer patients may be associated to complicating conditions such as inflammation." (PMID 32971853, 2020). "Prior research has emphasised the vital function of FN1 as a pivotal regulator implicated in diverse facets of cancer progression, encompassing cellular evolution, proliferation, viability, movement and blood vessel formation, in numerous forms of human cancer." (PMID 37784253, 2023). "Consequently, these cells were labelled FN1 cancer‐associated fibroblasts (FN1CAFs)." (PMID 37784253, 2023). "Furthermore, FN1 expression has been associated with cancer progression in several types of tumors." (PMID 36362243, 2022). "Moreover, FN1 expression has been demonstrated to be closely associated with various migration processes, including wound healing, embryogenesis, and metastasis of cancer cells." (PMID 34093898, 2021). "Moreover, cancer-associated fibroblasts assemble FN1 and trigger invasion through integrin-αvβ3." (PMID 30736807, 2019). "The major feature segregating them from non-PMC42 cancer lines is high levels of mRNAs encoding hallmark components of the BM, such as collagen (various collagens, including type IV, preferred by mammary epithelium), fibronectin (FN1), and laminins (subunits α1, α4, β1, and γ1)." (PMID 18588681, 2008). "When evaluating the genes in vitro, only FN1 showed a significant correlation (p=0.0256) with AUC radiosensitivity values in a panel of 535 cancer cell lines from the CCLE." (PMID 40792276, 2025). "Within the FN1 pathway, Fn1-Cd44, Fn1-Sdc1, and Fn1-Sdc4 mediated intercellular communication among cancer cells, with Fn1-Cd44 being the most potent ligand–receptor pair." (PMID 40723284, 2025). "We have shown that the mechanism involved appears to be through cytokines such as EGF, PDGF, TNF-α, IFN-γ or IL-6, which activate signaling pathways within the cancer cells themselves that lead to FN1 production." (PMID 40096084, 2025). "Since FN1 is highly glycosylated and involved in many aspects of cancer metastasis, we next focused on it." (PMID 40096084, 2025).
cancer (continued). "In cancer zone A, cancer cells primarily engaged in Col1a1/Col1a2-Itga9/Itgb and Fn1-Cd44 interactions to promote invasion and drive ECM remodeling." (PMID 40723284, 2025). "We also confirmed that platelets can stimulate FN1 transcription in cancer cells using cancer cells underexpressing FN1 by 2-fold." (PMID 40096084, 2025). "In cancer zone A, Col1a2-Itga9/Itgb1 and Fn1-Cd44 interactions among cancer cells, along with Angptl4-Sdc2 signaling between CAFs 1 and cancer cells, collectively activated stromal remodeling and promoted EMT." (PMID 40723284, 2025). "C3 FN1+ TCs were posited as essential for understanding carcinogenesis and evolution, derived from developmental trajectories of ovarian to omental cancer tissues." (PMID 40612060, 2025). "FN-1 (Fibronectin 1) is generally considered an oncogene promoting cell adhesion, migration, and invasion in ovarian and other cancers." (PMID 41382114, 2025). "Altogether, our findings unveil CPLF as a data-inherent multi-omics prognostic factor and establish the CPLF/FN1/integrin axis as a key pathway mediating myofibroblast–cancer cell crosstalk in CRC progression." (PMID 41405822, 2025). "In particular, FN1, VCAN, and LRRC15 are markers of BMSCs which also co-modularized with COL10A1 in cancer; all three genes are involved in cell migration, and FN1 contributes directly to osteoblast mineralization as well as metastasis." (PMID 39939916, 2025). "FN1 promotes the migration and invasion of GBM cells and is a key candidate for mediating the function of cancer-associated fibroblasts." (PMID 40365337, 2025). "Our first step was to examine, using untouched holotomographic microscopy, the effect of FN1 underexpression on cancer cell death." (PMID 40096084, 2025). "Studies have highlighted that in oral and mammary squamous cell carcinomas, FN1 undergoes a specific glycosylation that contributes to cell invasion and multidrug resistance of cancer cells." (PMID 40096084, 2025). "This discovery aligns with previous studies indicating that FN1 activates pro-survival signals through integrin receptors in various cancers." (PMID 40678072, 2025). "Staining for the CAF marker α-SMA and the ECM component fibronectin (FN1)—and thus the influence of cancer cell phenotype on the fibroblasts—was inconclusive." (PMID 41228193, 2025). "FN1 have been suggested to promote radioresistance in head and neck, and it is known to increase cancer cell survival after radiation in clonogenic assays." (PMID 40792276, 2025). "Mechanistically, BPS can increase the expression of fibronectin (FN1), a robust mesenchymal marker of cancer cells, by promoting the binding between ERRα and the FN1 promoter." (PMID 40116906, 2025). "Given our previous findings on the variations in GT expression in platelet-educated cancer cells, it would be valuable to further investigate the glycosylation of FN1." (PMID 40096084, 2025). "We confirmed this result by Western-blotting, demonstrating an overexpression of FN1 in platelet-educated cancer cells." (PMID 40096084, 2025). "Within the main cluster in red, one glycoprotein appeared to be central, fibronectin (FN1) which is overexpressed by 166% in platelet-educated cancer cells." (PMID 40096084, 2025). "Fibronectin 1 (FN1) is a widely distributed glycoprotein in the extracellular matrix that plays a crucial role in cancer onset and development." (PMID 39323640, 2024). "A previous study demonstrated that under hypoxic conditions, CEBPD can bind to the FN-1 promoter and activate FN-1 expression in cancer cells." (PMID 39025831, 2024). "FN1 plays a crucial role in PCa progression by promoting cancer cell adhesion, migration, invasion, and formation of the metastatic niche." (PMID 38017134, 2024). "The fibronectin-1 encoding gene (FN1), whose expression is increased in cancer cells, shows EMT plasticity and is often used as a biomarker of the mesenchymal phenotype." (PMID 38611032, 2024).
cancer (continued). "Our RNAseq analysis revealed consistent patterns of dysregulation for these biomarkers across all cancer stages, from Stage I to Stage IV, highlighting three of them: fibronectin 1 (FN1), coagulation factor V (F5), and thrombospondin 1 (THBS1)." (PMID 39456895, 2024). "While UBE2M, is only recently starting to be envisaged as a cancer player, FN1 and RECQL4 are two well-known oncogenes." (PMID 39657701, 2024). "Previous studies have also reported dysregulation of COL1A1, COL1A2, COL3A1, and FN1 promoter methylation in various cancers." (PMID 38913913, 2024). "Although FN1 plays a role in the wound healing process, cancer and wound healing share common cellular and molecular pathways that operate in a delicate balance to maintain tissue homeostasis." (PMID 39456895, 2024). "Our studies demonstrated that FN1 and COL11A1, targets that are associated with the matrisome, are expressed by cancer cells." (PMID 38702309, 2024). "Both FN1 and F5 were found to be positively regulated in cancer samples, with this trend observed uniformly across each stage." (PMID 39456895, 2024). "This is an intriguing finding, and suggests that THUMPD3 contributes to cancer progression, at least in part, by maintaining inclusion of a cancer promoting exon in FN1." (PMID 39656728, 2024). "Genes potentially associated with cell migration and cancer metastasis included CNTN5, FN1, Integrin Subunit Beta 6 (ITGB6), EPHB1, Unc-5 Netrin Receptor D (UNC5D), SDK1, RADIL, LRRC7, PCDH11X, and ADAMTS9." (PMID 39770638, 2024). "The correlation between FN1 mRNA levels and the prognosis of GC patients was performed using bioinformatic analyses of the Asian Cancer Research Group (ACRG) and TCGA-STAD cohorts." (PMID 37771777, 2023). "FN1 is a glycoprotein that upregulates expression levels of matrix metalloproteinases to promote cancer cell local invasion and distant metastasis, and its overexpression in NPC is closely related to an advanced stage and poor survival." (PMID 37056700, 2023). "Among the downstream genes, FN1, cadherin 2 (CDH2), EGFR, integrin subunit alpha 6 (ITGA6), and integrin subunit beta 4 (ITGB4), which are widely studied and are associated with cancer metastasis, were selected for further investigation." (PMID 37096833, 2023). "The correlation between the FN1 protein expression level and the prognosis or clinicopathology of patients with cancer remains inconclusive, especially in GC." (PMID 37771777, 2023). "The FAK/ILK/ERK/PI3K/NFB pathways are activated when FN1 binds to integrin, which causes overexpression of MMP-2 and MMP-9 and the destruction of the extracellular matrix (ECM) as well as the invasion of cancer cells." (PMID 37640804, 2023). "Among other alterations inhibiting apoptosis, it has been observed that fibronectin 1 (FN1) impedes the apoptosis of cancer cells and increases their migratory capacity and invasion through the focal protein adhesion kinase (FAK) signaling pathway." (PMID 36831674, 2023). "FN1 is a gene commonly reported in gene expression studies related to cancer and neurodegenerative diseases." (PMID 36979356, 2023). "Due to the characteristics of participating in the recurrence and metastasis of a variety of cancers, Fn-1, S100A8, S100A9, and MMP9 were regarded as the main components of the formation of the pre-metastatic microenvironment." (PMID 37330523, 2023). "Using the tandem mass tag (TMT) method, the authors showed that high levels of total and phosphorylated fibronectin 1 (FN1), haptoglobin (HP), S100A9, and fibrinogen α-chain (FGA) in EVs of CRC blood samples were associated with cancer progression." (PMID 37241967, 2023).
cancer (continued). "The 5 members of the M0-ECM signature, FN1, VCAN, COL11A1, SFRP2, and MXRA5, have been associated with cancer progression, through markers of prognosis or the process of metastasis." (PMID 37188691, 2023). "CM samples from the cancer cells with downregulated or upregulated FN1 were used to treat HUVECs to perform tube formation assays and 3D spheroid sprouting assays." (PMID 36999964, 2023). "This study revealed the significant effects of FN1 3′-UTR on cancer invasion and metastasis and elucidated the complete ceRNA regulatory network related to FN1 3′-UTR." (PMID 37771777, 2023). "The application of the Gene Expression Profile Interactive Analysis (GEPIA) platform 27 and clinical patient tissue validation revealed that FN1 mRNA expression was significantly higher in cancer tissues than in adjacent tissues." (PMID 37771777, 2023). "Individual proteins, such as fibronectin 1 (FN1), have previously been found in cancer-associated vesicles." (PMID 37241967, 2023). "When looking at individual cancer types, Exon A exhibited higher normalized expression than the FN1 gene in 17 out of 25 (68%) cancer types, while Exon B exhibited higher normalized expression in 19 out of 25 (76%) cancer types." (PMID 36899821, 2023). "Among them, TIMP1, LGALS3BP, A2M, AHSG, FN1, HRG, and ITIH4 have been associated with cancer, while CF I, C2, and C4A, have been related to complement activity." (PMID 37685286, 2023). "Fn1(fibronectin-1) is a member of the glycoprotein family that has been shown to play an important role in cancer metastasis, osteogenic differentiation, and epithelial-mesenchymal transformation(EMT)." (PMID 37974089, 2023). "Our study provides preliminary evidence that FN1 plays a pro-cancer role in ESCC, which is consistent with previous findings on the role of FN1 in different types of cancer." (PMID 37026938, 2023). "FN1 was significantly elevated in several malignant tumors, which is in accordance with our results." (PMID 36389789, 2022). "FN1 is also involved in certain cancer metastasis-related GO processes such as regulation cell adhesion and extracellular structure organization." (PMID 35280793, 2022). "The increased expression of FN1 gene has been reported in many types of cancer, including gastric, breast, thyroid, renal and ovarian cancers." (PMID 35742950, 2022). "Many of the ECM components that showed differential expression and were highlighted in the hypernetwork analysis, including MMPs, TIMP3, FN1, LAMC1, and COL4A1/6A2, have previously been reported as prognostic or diagnostic markers in different cancers." (PMID 35267606, 2022). "Similar to FN1, in cancer, OPN is overexpressed by tumoral parenchymal and stromal cells, and it has been implicated in invasion, metastasis, and treatment resistance." (PMID 36146635, 2022). "FN1 promotes cancer cell proliferation, survival, migration, and invasion through focal adhesion kinase activation and stimulates angiogenesis by exhibiting proangiogenic effects associated with AKT signaling." (PMID 35457039, 2022). "By contrast, the FN1-related molecular pairs, including FN1-CD44 (a marker of cancer stem cells) and FN1-(ITGAV + ITGB1), were prompted between SELENOP-Mφ/SPP1-Mφ and FABP4-Mφ/FCN1-Mφ/CD4/CD8 cells in LUAD." (PMID 36008393, 2022). "Fibronectin 1 (FN1) is a glycoprotein found throughout the extracellular matrix that has a role in the onset and progression of cancer." (PMID 36081567, 2022). "ECM-receptor interaction, TGF-beta signaling pathway, focal adhesion, O-glycan biosynthesis, and pathways in cancer were significant pathways in the FN1 high-expression phenotype." (PMID 36035176, 2022). "As a gene correlated with cell adhesion and ECM remodeling, FN1 inhibits apoptosis, promotes epithelial cell migration, and drives cancer development." (PMID 36035176, 2022).
cancer (continued). "PIK3R2 and FN1 resulted being the proteins with the highest number of protein-protein interactions, and therefore can be considered as pan-cancer gene hubs." (PMID 36329531, 2022). "FN1 also has been found to be involved in the regulation of innate immune response and to be correlated with immune infiltrates in cancers." (PMID 36387401, 2022). "FN1 is involved in the occurrence and development of various tumors and is upregulated in multiple cancer types." (PMID 35252204, 2022). "FN1 is primarily expressed in fibroblasts but can also be produced by other cell types, including cancer and endothelial cells." (PMID 35216235, 2022). "FN1 soluble into the plasma has been proposed as a promising tool for cancer screening based on preclinical and clinical data." (PMID 33731188, 2021). "In recent studies, the activation of the PI3K/Akt signaling pathway has been shown to be instrumental for FN1 transcription and alternative splicing, modulating cell behavior in various cancers." (PMID 34758823, 2021). "FN1 has been shown to beupregulated in different types of cancer and promotes cancer growth, progression, invasionand metastasis; and thus, is proposed as a target for cancer imaging and treatment." (PMID 33884102, 2021). "Cancer cells attached to FN1 show enhanced clusters of β1 integrin, which initiate its downstream signaling, upon treatment with radiotherapy, paclitaxel, mitomycin and cisplatin." (PMID 33731188, 2021). "For instance, the prosurvival effect that FN1 has on cancer cells is primarily mediated by FAK-dependent activation of the PI3K/AKT/mTOR pathway." (PMID 34758823, 2021). "A significant increase in FN1 mRNA expression was observed in the triple culture (MSChigh) compared to the cancer cells alone or cancer cells embedded with THP-1." (PMID 34885111, 2021). "Regarding the proteins involving malignant phenotypes, the FN1 protein was found to be associated with PI3K/AKT and its pathway in cancer." (PMID 33805467, 2021). "Elevated expression of FN1 cluster 8 is of interest, because FN1 is an important gene involved in the development of various cancer types driving proliferation." (PMID 34006939, 2021). "Because SNAI1, FN1, and MMP9 play a key role in inducing EMT-associated cancer plasticity, chemoresistance, and metastasis, we aimed to define the pivotal role of AURKA in mediating TGF-β-induced expression of SNAI1, FN1, and MMP9 genes." (PMID 33674749, 2021). "In this section, we will discuss FN1 delivery by EVs, the role of EVs in FN1-driven signaling and the potential use of FN1 included in EVs as a cancer biomarker." (PMID 33731188, 2021). "When cancer occurs, fibronectin 1 expression increases, promoting adhesion and invasion of cancer cells and increasing the damage to normal tissues." (PMID 33728331, 2021). "Plasmatic FN1 promotes lung metastasis in a murine model and contributes to fibrin clot formation and cancer invasion by activating αvβ3 integrin." (PMID 33731188, 2021). "FN1 has been related to therapy resistance in cancer and FN1 is one of the most altered gene related to cisplatin resistance." (PMID 33731188, 2021). "MEXPRESS was used to investigate the correlation between gene expression and DNA methylation; the correlations between FN1 and cancer immune infiltrates were investigated using CIBERSORT." (PMID 35141255, 2021). "To validate the clinical relevance of our findings, we first used The Cancer Genome Atlas (TCGA) transcriptomics microarray data of 538 chemo-naïve OC samples to assess survival associations of COL6, FN1, and VTN expression." (PMID 34162871, 2021). "Analysis of FN1 expression in the sequential sections showed that SPARC expression in cancer cells was adjacent to FN1 expression in the surrounding stromal tissue." (PMID 33579227, 2021). "Lung-derived CD44low cells also exhibited upregulated levels of genes associated with mesenchymal cells and more dedifferentiated phenotypes in advanced cancers (e.g., FN1 and POFUT2)." (PMID 34579762, 2021).